IGF1 (insulin like growth factor 1)
Diseases named in the same sentence as IGF1 in open-access papers (continued):
Sharing a sentence is not in itself a finding about the gene and the disease.
ischemia (63 papers, 2005 to 2025). A hypoperfusion of the BLOOD through an organ or tissue caused by a PATHOLOGIC CONSTRICTION or obstruction of its BLOOD VESSELS, or an absence of BLOOD CIRCULATION. "Another descriptive study investigated the partial deficiency of IGF-1 and its influence on the heart and coronary circulation before and after ischemia–reperfusion (I/R)." (PMID 35890161, 2022). "The main outcome of this work is that the subacute administration of zinc increases the expression of CCL2, CCR2, and growth factors (FGF2 and IGF-1) as well as preventing the loss of memory in the rats after transient hypoxia-ischemia." (PMID 26355725, 2015). "In ischemia/reperfusion injured brains, an increase of IGF‐1 secretion and GLUT3 upregulation, are regarded as protective processes." (PMID 38887182, 2024). "IGF-1 is renowned for its neuroprotective effects post-ischemia, and IGF-1 expression levels in rats were found to be significantly lower in female astrocytes from the age of 10–12 m as compared to younger female astrocytes." (PMID 39451242, 2024). "MerTK+ macrophages secrete IGF1 to promote angiogenesis, which is a crucial process for cardiomyocyte sustainability during ischemia." (PMID 39195894, 2024). "In conclusion, our findings demonstrate that α2A- adrenergic molecule-primed neuronal cells possess to release IGF1, activate Akt, and protect by themselves from damage under ischemia." (PMID 39545230, 2024). "We further verified the features of the Mrc1+ Igf1+ macrophage subset in a unilateral ischemia-reperfusion injury (IRI) model (GSE174324)." (PMID 38389846, 2024). "Another direction of research on the effectiveness of INI and intranasally administered IGF-1 in experimental ischemia is the study of the potentiation of its neuroprotective effect when used together with other drugs that have neuroprotective properties." (PMID 36834685, 2023). "Systemic recombinant IGF-1 administration has been shown to significantly attenuated ischemia injury-induced microglial activation, cerebral edema, and improved sensorimotor function." (PMID 36181630, 2023). "IGF-1 is otoprotective against cochlear insults, such as aminoglycosides, noise exposure or ischemia." (PMID 36829792, 2023). "At the same time, a number of studies have shown the effectiveness of the protective effects of intranasally administered IGF-1 on the white matter of the brain under the conditions of hypoxia and ischemia." (PMID 36834685, 2023). "Macrophages expressing high levels of F4/80 upregulate insulin-like growth factor 1 (IGF-1) during mouse skeletal muscle recovery following ischemia-reperfusion injury, and intramuscular injection of F4/80Hi macrophages enhances healing." (PMID 35837290, 2022). "We measured Igf1 and Igfp3 levels in the blood 2 days after ischemia using an ELISA to examine the effects of Zfp580 on post-ischemic endocrine regulation." (PMID 35557964, 2022). "Igf1 expression was selectively induced in the ipsilesional hemisphere starting 2 days after ischemia." (PMID 35557964, 2022). "Animal experiments and in vitro studies have shown that IGF-1 protects HCs against damage from noise exposure, ischemia, and ototoxic drugs." (PMID 36330225, 2022). "Increased regeneration has been proposed as a mechanism of skeletal muscle fiber hypertrophy in response to IGF1 overexpression and endurance exercise training and protection against ischemia‐induced muscle atrophy." (PMID 35199907, 2022). "The PPAR/IGF-1 pathway protects cardiomyocytes against apoptosis induced by ischemia and reperfusion or biomechanical stress." (PMID 33807089, 2021). "As a net result, the percentage of GFAP+/IGF-1+ double-positive cells among the GFAP+ astrocytes was significantly increased from 50.79 ± 8.97% in the ischemia control group to 78.70 ± 20.11% in the MSC group." (PMID 32952570, 2020). "Huang and group showed the role of modRNA-delivered insulin-like growth factor-1 (IGF1) in providing cardioprotection in CM after ischemia and MI." (PMID 32822006, 2020).
ischemia (continued). "Previously, we found that in the ischemia brain cortex of dMCAO model, IGF-1 was partially expressed by NeuN+ neurons and CD68+ microglia/macrophages." (PMID 32952570, 2020). "The IGF-1 level in peripheral blood plasma was significantly higher in the MSC group than in the ischemia control group." (PMID 32952570, 2020). "The concentration of IGF-1 in the blood plasma (172.7 ± 35.9 ng/mL) of ischemia group was lower than that of sham group (246.9 ± 44.5 ng/mL)." (PMID 32952570, 2020). "Knockdown of neuronal insulin-like growth factor 1 receptor (IGF-1R) exacerbates hypoxic injury and increases mortality in mice, and IGF-1R is required in order for IGF-1 to protect myocardial cell exposed to ischemia." (PMID 31246952, 2019). "Tejada and colleagues suggested a detrimental role of mMCP-4 in the degradation of IGF-1 during ischemia-reperfusion injury in the mouse." (PMID 30233357, 2018). "Here we showed that Aβ toxicity and ischemia provoked substantial region-specific increases in the abundance of cells staining for IGF-1 and IRS-1 that encompassed the majority of the ipsilateral hemisphere." (PMID 29572520, 2018). "By 14 days post-ischemia, TNFα and IL-1β levels tended to come back down, whereas the expression of IGF-1 were increased, similar to our astrocyte-activated microglial cultures." (PMID 29764475, 2018). "Endothelial cells under oxygen-glucose deprivation, in a cell culture model of ischemia, secrete IGF-1." (PMID 30374291, 2018). "The combination of IGF-1 and hypothermia was tested in a study in which rats were subjected to global ischemia lasting 8 min." (PMID 29896438, 2018). "Studies in different lesion models such as ischemia and traumatic brain injury have shown increased production of insulin-like growth factor 1 (IGF-1) and interleukin-1β (IL-1β) by glial cells." (PMID 25352772, 2014). "IGF-1 has been shown in preclinical models to aid in survival of myocardium in the setting of ischemia." (PMID 24458261, 2014). "IGF-1 protects HCs from various injuries to the inner ear, including noise exposure, ischemia, and aminoglycoside treatment." (PMID 25309440, 2014). "In this regard, it is noteworthy that insulin growth factor-1 (IGF-1), a cytokine known to be synthesized by M2 macrophages, was previously shown to prevent ischemia-induced neuron cell death." (PMID 23825621, 2013). "In conclusion, ischemia-reperfusion injury is the strongest stimulus for activation of endogenous cardiomyocyte regeneration, correlating to the endogenous up-regulation of IGF-1 and HGF." (PMID 22590612, 2012). "Our findings that the rRNA is increased agree with the report that local insulin-like growth factor-1 (IGF-1) mRNA is increased in rat gastrocnemius following 2 hours of ischemia and 7 days of reperfusion." (PMID 22027257, 2011). "In a recent study IGF-1 has been identified as one of the upregulated diffusible factors involved in promoting neural progenitor proliferation after focal ischemia." (PMID 17440609, 2007). "Seemingly, bulk flow of CSF plus any edema fluid formed within the parenchyma is needed to transport IGF-1 as widely as appears to be the case in the hypoxia-ischemia model." (PMID 16045806, 2005). "In BMDJ/FDOJ, IGF1 upregulation may indicate a compensatory response to chronic ischemia and bone degeneration." (PMID 40426971, 2025). "However, it should be noted that, in contrast to neurons, data on the protective effects of insulin and IGF-1 in microglia and oligodendrocytes during ischemia and TBI remain poorly understood." (PMID 36834685, 2023). "While these neuroprotective effects are also well documented for other neurodegenerative and neurotraumatic conditions, including amyotrophic lateral sclerosis and ischemia, reductions in IGF-1-mediated signaling, on the other hand, have been shown to delay amyloid-β proteotoxicity in mice." (PMID 38094080, 2023).
ischemia (continued). "In animal models of ischemia, administering exogenous IGF-1 using various routes of administration (intranasal, intravenous, subcutaneous, or topical) at various time points before and/or following the insult, attenuated the neurological damage and accompanying behavioral changes." (PMID 35203315, 2022). "The IGF-1 Ec peptide, also known as mechano-growth factor (MGF), is up-regulated in exercised and damaged muscles, plays a neuroprotective role against ischemia and contributes to the actions of IGF-1 to improve cardiac function and activate resident stem cell populations." (PMID 33557137, 2021). "In conclusion, ischemia-reperfusion injury was the strongest stimulus with both global and focal cardiomyocyte progenitor cell marker up-regulations, correlating to the endogenous up-regulation of the growth factors IGF-1 and HGF." (PMID 22590612, 2012). "Similarly, the concentrations of IGF-1 in the ischemia group were 178.2 ± 33.5 ng/mL and 188.7 ± 34.5 ng/mL at days 4 and 7, respectively, which were significantly increased following MSC treatment to 233.1 ± 18.9 ng/mL (p < 0.05) and 245.8 ± 25.7 ng/mL, respectively (p < 0.05)." (PMID 32952570, 2020). "Following neurotoxic lesions such as ischemia, or injury to the cortex or the spinal cord, insulin growth factor-1 (IGF-1), and its receptors are found to increase in associated brain lesions, implying a role of IGF-1 in the pathological response to these brain insults." (PMID 31338023, 2019). "Thus, IGF-1/GSK-3β signaling might be critical for ischemia-induced neuronal hyperproliferation in the hippocampal dentate gyrus region." (PMID 27866373, 2017). "The stable expression of IGF-1 allows cells or tissues to resist damage in the course of MIRI, protects cardiomyocytes from ischemia-induced injury, and improves patients prognosis." (PMID 38428899, 2024). "In animals, increased levels of IL-10, enhanced expression of tumor growth factor β (TGF-β) and insulin-like growth factor-1 (IGF-1), suppress the activities of Th1 and Th2 lymphocytes after ischemia, thereby inducing neuroprotection." (PMID 35280892, 2022). "Astrocytic overexpression of IGF-1 also protected neurons against TBI by CCI, while astrocyte-IGF-1 gene transfer improved outcomes in rats following ischemia/perfusion." (PMID 30699952, 2019). "Additionally, immunofluorescence staining revealed the significantly elevated proportion of IGF1+ and TREM2+ microglia after ischemia, further confirmed those molecular signatures identified by snRNA‐seq and Bulk‐RNA‐Seq analysis." (PMID 38151703, 2024). "This hypothesis is further supported by a recent study by Ellison and coworkers, where intra-coronary delivery of IGF-1/HGF significantly increased c-Kit+/Nkx2.5+ cardiac progenitor cells in the infarct and border regions in a pig ischemia model." (PMID 22590612, 2012). "Additionally, the already-induced ischemia upregulates the secretion of VEGF, which may be further elevated by the fact that, as the neonate grows, IGF-1 levels increase, thus exacerbating pathological revascularization." (PMID 40362726, 2025). "Rather, it appears to result from a deficiency in the secretion of pro-regenerative cytokines like IGF1 by macrophages, facilitating at least in part, the premature differentiation of MuSCs/MPCs and ultimately the failure of muscle regeneration in BALB/c mice following hindlimb ischemia." (PMID 37950327, 2023). "In this study, we examined the histological presence of insulin-like growth factor-I (IGF-1) and insulin receptor substrate (IRS-1) in anatomically distinct brain circuits compared with morphological brain damage in a co-morbid rat model of striatal ischemia (ET1) and Aβ toxicity." (PMID 29572520, 2018).
Cachexia (60 papers, 2007 to 2026). Severe weight loss, wasting of muscle, loss of appetite, and general debility related to a chronic disease. "We analyzed expression of several transcripts associated with cachexia, including C‐reactive protein (Crp), insulin‐like growth factor 1 (Igf‐1), IL‐1ß (Il‐1b), IL‐6 (Il‐6), and TNF (Tnf)." (PMID 32039522, 2020). "In summary, the %MPS reduction during the initiation of cachexia is associated with IGF-1/mTOR signaling repression, while muscle AMPK activation and activation of ATP independent protein degradation occur later in the progression of cachexia." (PMID 21949739, 2011). "Magnolol, known to suppress muscle protein degradation, inhibit inflammatory responses, and increase IGF-1-mediated protein synthesis, is a promising supplement for preventing chemotherapy-induced skeletal muscle atrophy associated with cancer-related cachexia." (PMID 33804803, 2021). "Igf1 modifiers that are co‐regulated during toxin‐induced weight loss (Igfbp1, Igfbp2, and Igfals) are also worthy of consideration as druggable targets in cachexia." (PMID 30782979, 2019). "Circulating and muscle-specific IGF-1 levels are reduced in animal models of cancer cachexia (e.g., AH-130 hepatoma and C26 colon adenocarcinoma), correlating with the loss of muscle mass." (PMID 40869331, 2025). "It has been shown that ghrelin can indirectly increase muscle mass by stimulating food intake, activating the GH/Insulin-like growth factor-1 (IGF-1) axis in cachexia mice, and promoting myocyte differentiation and fusion in C2C12 myoblasts." (PMID 40429895, 2025). "For a biomarker to be responsive to change, it must be related to the mechanism of action of the intervention and/or the underlying cachexia process that is modified by the intervention, as seen with IGFBP‐3, IGF‐1 and anamorelin." (PMID 38783477, 2024). "Regarding muscle synthesis, the low IGF-1 blood levels in the rats in our model concurred with the observations reported in other cancer cachexia models." (PMID 37893197, 2023). "IGF-1 (insulin-like growth factor 1) is sensitive to food intake and blocks in physiological conditions the myostatin pathway, thus preventing cachexia." (PMID 38067294, 2023). "Hormonal signals involved in cachexia include insulin and insulin growth factor 1 (IGF-1), leptin, ghrelin, melanocortins, neuropeptide Y and growth hormone." (PMID 35326490, 2022). "Sepsis increases glucocorticoid and decreases IGF-1, leading to skeletal muscle wasting and cachexia." (PMID 35408999, 2022). "Local and serum levels of pro-inflammatory cytokines are elevated in cachexia patients, resulting in impaired IGF-1 response to GH, while low levels of IGF-1 are associated with reduced leg muscle cross-sectional area and strength." (PMID 36139760, 2022). "In cachexia, insulin receptor, GH, and IGF-1 pathways; peroxisome proliferator-activated receptor gamma (PPARγ) agonists; angiotensin II inhibitors; and testosterone are possible therapeutic targets." (PMID 35565236, 2022). "Taking into account that IGF-1 is a hormone that prevents muscle atrophy and increases muscle mass, the down-regulation of circulating and muscle IGF-1 plays an important role in inflammation-induced cachexia." (PMID 34502376, 2021). "All these data suggest that during inflammation, the decrease in serum and muscle IGF-1, together with the increase in muscle IGFBP-3, are associated with the increase in muscle proteolysis and cachexia." (PMID 34502376, 2021). "In the ApcMin/+ mice, a model of colorectal cancer that develops cachexia, muscle IGF-1 mRNA expression was decreased with suppressed mTOR targets." (PMID 32858949, 2020). "Using the Ang II-induced cachexia model, IGF-1 or ghrelin was previously shown to suppress body weight reduction and increase food intake volume." (PMID 31667435, 2019).
Cachexia (continued). "Growth factors, which are important for adipogenesis, are downregulated in catabolic states and cachexia, which are characterized by low levels of insulin growth factor 1 (IGF-1) and increased levels of transforming growth factor beta (TGF-β) family members." (PMID 27900559, 2017). "To evaluate changes in cellular signaling involved in the regulation of protein synthesis, we measured IGF-1/Akt/mTOR pathway activation during the initiation and progression of cachexia." (PMID 21949739, 2011). "None of the reports of ghrelin administration in colitis have included levels of growth hormone or IGF-1, though studies of GHS-1a agonist treatment in cachexia have reported increased levels of IGF-1." (PMID 21845198, 2011). "In summary, our data show muscle protein synthesis and related IGF-1 signaling is suppressed during the initial progression of cachexia in the ApcMin/+ mouse." (PMID 21949739, 2011). "Despite the reduction in IGF-1 expression and mTOR signaling, we detected an increase in Akt phosphorylation as cachexia progressed." (PMID 21949739, 2011). "In the present study, we show that a reduction in muscle IGF-1 gene expression is an early event that occurs during the initiation of cachexia, and expression is further repressed as cachexia progresses." (PMID 21949739, 2011). "In summary, exercise counteracts muscle wasting in cachexia by simultaneously promoting muscle protein synthesis via the IGF-1/PI3K/Akt/mTOR pathway and suppressing excessive protein degradation mediated by the ubiquitin-proteasome and autophagy-lysosomal pathways." (PMID 40869331, 2025). "However, in various forms of muscle atrophy, IGF-1 expression is downregulated, often occurring before the onset of cachexia." (PMID 40104495, 2025). "Moreover, it indirectly improves muscle mass by stimulating the insulin-like growth factor 1 (IGF1) pathway in mice with cachexia." (PMID 35781838, 2022). "When respiratory muscles are impacted by COPD, skeletal muscle wasting or cachexia often develops, in which insulin-like growth factor 1 (IGF-1) signaling plays a major role in promoting disease onset and progression, resulting from the activation of the mTOR signaling pathway." (PMID 32722591, 2020). "Further study about the comparison between HPE treatment and other previously reported remedies (IGF-1 and ghrelin) could help to define its therapeutic value for the treatment of cachexia." (PMID 31667435, 2019). "Muscle IGF-1 mRNA expression decreased 28% (P = 0.001) during the initiation of cachexia." (PMID 21949739, 2011). "Moreover, cachexia of dialysed patients arises as a result of a complex interplay of acidosis, a decreased response to anabolic hormones [insulin, insulin-like growth factor-1 (IGF-1)] and chronic inflammation." (PMID 18253763, 2009). "Consequently, while reducing IGF-1 levels may be advantageous in the context of cancer prevention, it could be detrimental by exacerbating muscle wasting (cachexia) in cancer patients or impairing muscle growth in healthy individuals." (PMID 40566597, 2025). "Interestingly, the reduction of IGF-1 was observed irrespective of the weight loss, suggesting that IGF-1 downregulation precedes cachexia development." (PMID 32858949, 2020). "Muscle IGF-1 mRNA expression and mTOR targets were suppressed with the progression of body weight loss, while muscle AMPK phosphorylation (Thr 172), AMPK activity, and raptor phosphorylation (Ser 792) were not increased with the initiation of weight loss, but were induced as cachexia progressed." (PMID 21949739, 2011). "Chronic inflammation suppresses the hypothalamic GH-IGF-1 axis, leading to reduced circulating IGF-1 levels, increased protein breakdown, and the development of skeletal muscle atrophy and cachexia." (PMID 40104495, 2025).